BRAF (B-Raf proto-oncogene, serine/threonine kinase)
Diseases named in the same sentence as BRAF in open-access papers (continued):
Sharing a sentence is not in itself a finding about the gene and the disease.
acral melanoma (62 papers, 2009 to 2026). "Upon evaluation, globulin levels, having more than three metastases, BRAF mutation, and acral melanoma were found to be associated with resistance." (PMID 41010951, 2025). "Their findings indicate that, in acral melanomas, high BRAF expression is associated with an immunosuppressive microenvironment." (PMID 41002140, 2025). "In acral melanoma, BRAF (9%), NRAS (17%), KRAS (8%), KIT (19%), and NF1 (7%) mutations were detected." (PMID 39564955, 2024). "Efficacy was observed across subgroups by PD-L1 expression and BRAF mutation status, with notable benefit in patients with acral melanoma who had PD-L1–positive or BRAF wild-type disease." (PMID 36304457, 2022). "Human acral melanomas have also been studied at the genetic level, with mutations of BRAF (21.3%) and KIT genes (11.5%; 50% within exon 11) standing out." (PMID 35202309, 2022). "TERT promoter mutations were found in 4 cases (13%): two acral lentiginous melanomas also harbored a BRAF mutation, another a NRAS mutation, while a nodular melanoma harbored a NF1 mutation." (PMID 33917086, 2021). "Nonetheless, the frequency of BRAF mutations in acral melanoma is relatively low, limiting the clinical benefit of BRAF and MEK inhibitors in this patient population." (PMID 34149718, 2021). "Nevertheless, dabrafenib plus trametinib demonstrated preliminary clinical benefit in acral melanoma cases with BRAF V600 mutations." (PMID 34504796, 2021). "BRAF mutations were found in all the four histotypes, with a frequency of 32% in acral lentiginous melanoma." (PMID 33917086, 2021). "We also found, for the first time, that BRAF V600E positivity and BRAF V600E heterogeneity were significantly associated with worse patient survival in acral melanoma." (PMID 32143442, 2020). "One sample classified in the RAS group with BRAF mutation was observed in acral melanoma (1/20, 5%)." (PMID 32083130, 2020). "All the acral melanomas in our study were situated on palms and soles, on which lower frequency of BRAF mutations was demonstrated than that on dorsal acral sites." (PMID 32083130, 2020). "In this study, we aimed to further elucidate the roles of BRAF V600E status and BRAF V600E heterogeneity in a larger number of patients with acral melanoma (n = 112) and to look at possible associations between these statuses and patient survival." (PMID 32143442, 2020). "Further investigation is warranted to examine the possible association between BRAF heterogeneity and the response to BRAF inhibitors in acral melanoma." (PMID 32143442, 2020). "Our study reveals that VE1 immunostaining is a useful ancillary method for detecting BRAFV600E mutations in acral melanoma and allows for a clear visualization of intra- and inter-tumor BRAF heterogeneity." (PMID 31817947, 2019). "In acral melanoma, BRAF and NRAS are still the most frequent mutations present (although less frequent than in non-acral cutaneous melanoma), followed by NF1 and KIT mutations." (PMID 30995742, 2019). "Nodular melanomas are known to have BRAF V600 mutation rates approximately twice higher than acral lentiginous melanomas." (PMID 31890008, 2019). "Regarding BRAF mutation studies, only one article has studied the BRAF V600 mutation prevalence among acral lentiginous melanoma in Indonesia so far." (PMID 31890008, 2019). "Further subgroup analysis in patients with acral melanoma by PD-L1 expression and BRAF mutation status within the current analysis showed particularly good response and prolonged survival in patients with PD-L1–positive and BRAF wild-type disease." (PMID 36304457, 2022). "Furthermore, a difference is also obvious between canine and human acral melanoma, in which BRAF and KIT mutations occur more frequently." (PMID 35202309, 2022).
acral melanoma (continued). "While, BRAF V600E mutation was less frequent in acral melanomas (1/18;6%)." (PMID 34102999, 2021). "The homogeneous and heterogeneous patterns of intratumor BRAF V600E illustrate the complexity and heterogeneity of acral melanoma, which might be due to the mutation of BRAF occurring at different stages of acral melanoma progression." (PMID 32143442, 2020). "We found driver mutations in the oncogene BRAF exclusively in patients with acral melanoma." (PMID 32110946, 2020). "However, only one acral melanoma (5%) was observed in a non-V600E BRAF mutation, which was less than that (8.9–30%) in other cohorts." (PMID 32083130, 2020). "The less frequency of BRAF mutation may be associated with the arising sites of the acral melanomas." (PMID 32083130, 2020). "We cannot currently provide a definite hypothesis about the causes of conflicting reports regarding intra-tumor BRAF heterogeneity, but the fact that we exclusively dealt with acral melanoma might have contributed to the high rate of heterogeneity reported." (PMID 31817947, 2019). "The BRAF mutation frequency of 67% in naevi is far higher than in acral melanoma (around 20%)." (PMID 30995742, 2019). "Therefore, the BRAFi+MEKi combination might be the preferred strategy for the acral melanoma subtype with BRAF V600 mutation." (PMID 34504796, 2021). "The mechanisms by which heterogeneous BRAF V600E expression is associated with worse patient survival are under investigation, and we speculate that acral melanomas with heterogeneous BRAF V600E have similar (or more aggressive) biological behavior to those with homogeneous BRAF V600E." (PMID 32143442, 2020). "Considering we detected no recurrent non-V600E BRAF, KIT, or NF1 mutations in naevi, this may imply that acral melanomas harboring these mutations arise primarily de novo, whereas BRAF V600E or NRAS Q61 mutant acral melanomas may more frequently arise from pre-existing naevi." (PMID 30995742, 2019). "Anti-PD1 and anti-CTLA4 combination therapies have been shown to be particularly beneficial for patients with BRAF-mutant acral lentiginous melanoma." (PMID 38390259, 2024). "In BRAF V600E-mutant acral melanoma, genomic sequencing has indicated that these lesions behave more like non-acral cutaneous melanoma as they lose some of the gene amplifications often noted in acral melanomas." (PMID 39001457, 2024). "Mutations in BRAF, NRAS, and KIT and amplifications of CCND1, CDK4, MITF, and TERT were well established in cases of acral melanoma." (PMID 36980308, 2023). "As a result, the activation of YAP in turn upregulates the expression of NRAS and BRAF genes, promoting the development of acral melanoma." (PMID 37894888, 2023). "Subgroup analysis suggested particular benefit in PD-L1–positive and BRAF wild-type acral melanoma, although small subgroup sizes preclude definitive conclusions." (PMID 36304457, 2022). "Median PFS was 3.4 months (95% CI, 2.7–5.3) in patients with BRAF wild-type acral melanoma and 1.9 months (95% CI, 0.5–2.6) in patients with BRAF-mutant disease." (PMID 36304457, 2022). "Median OS was 18.5 months (95% CI, 10.4–28.8) and 5.8 months (95% CI, 0.5–7.4) in patients with BRAF wild-type and BRAF-mutant acral melanoma, respectively." (PMID 36304457, 2022). "BRAF and NRAS mutations are common in acral melanocytic nevus, whereas acral melanoma shows lower rates of KIT, NF1, BRAF, and NRAS mutations and remarkable copy number variations in genes such as CCND1, CDK4, hTERT, PAK1, and GAB2." (PMID 35997352, 2022). "In a subgroup analysis of patients with acral melanoma by BRAF mutation status (BRAF wild type, n = 34; BRAF mutant, n = 4), ORR was 20.6% (95% CI, 8.7–37.9; 0 CR/7 PR) in patients with BRAF wild-type disease and 0% in the 4 patients with BRAF-mutant disease." (PMID 36304457, 2022).
acral melanoma (continued). "As about half of BRAF V600E-positive acral melanomas exhibited intratumorally heterogeneous VE1 expression, we next examined which clinicopathological factors were associated with BRAF V600E heterogeneity." (PMID 32143442, 2020). "In this study, we unexpectedly found a high frequency of intratumorally heterogeneous BRAF V600E expression in acral melanoma." (PMID 32143442, 2020). "Investigation on the efficacy of BRAF/MEK inhibitors to heterogeneous acral melanoma will be an interesting future work." (PMID 32143442, 2020). "We also found that patients with acral melanoma exhibiting BRAF V600E staining had significantly poor survival." (PMID 32143442, 2020). "In conclusion, about half of BRAF V600E-positive acral melanomas had intratumor BRAF V600E heterogeneity." (PMID 32143442, 2020). "We retrieved a total of 112 patients with primary acral melanoma and checked their BRAF V600E status using immunohistochemical staining of VE1 antibody." (PMID 32143442, 2020). "Third, some metastatic lesions of acral melanoma had a different BRAF status compared with primary lesions (inter-tumor heterogeneity)." (PMID 31817947, 2019). "Second, clear proliferations of subclones with different BRAF status can exist within a tumor (intra-tumor heterogeneity) in patients who have acral melanoma." (PMID 31817947, 2019). "Only a few reports have investigated the BRAF status of acral melanoma in comparison with primary and metastatic lesions, and these studies were limited by small sample sizes (range of 4–16 patients)." (PMID 31817947, 2019). "Bai and colleagues conducted a retrospective analysis in which 28 patients had BRAF V600E-mutated metastatic acral melanoma and an ORR of 38.1% following treatment with BRAF-targeted therapy, suggesting a lower response rate than those reported with BRAF-mutant non-acral cutaneous melanoma." (PMID 39001457, 2024). "BRAF mutations are more common in non-acral melanomas (50% vs. 20%) and occur in only 15–20% of acral melanomas." (PMID 36980308, 2023). "The data from this study may reflect the natural history of acral melanoma because only 1 out of 112 patients had received BRAF/MEK inhibitor treatment and the majority of our cohort, thus, had not undergone BRAF-targeted therapy." (PMID 32143442, 2020). "The roles of oncogenic BRAF mutations of acral melanoma in pathogenesis and patient outcomes have not been fully elucidated." (PMID 32143442, 2020). "Interestingly, about half (11 out of 21) of BRAF V600E-positive acral melanomas showed an intratumoral heterogeneous staining pattern (a mixture of positively and negatively stained cells or cell nests)." (PMID 32143442, 2020). "Among the 112 acral melanomas, BRAF V600E status was established using Food and Drug Administration (FDA)-approved companion diagnostic kits, the Cobas BRAF V600 Mutation Test (Roche Diagnostics, Mannheim, Germany), or the THxID-BRAF kit (bioMérieux, Lyon, France), in 15 acral melanomas." (PMID 32143442, 2020). "Since patients treated with a combination of BRAF + MEK inhibitors had better TTR than those treated with anti-PD-1 inhibitors, non-acral types with higher BRAF mutation were preferred for the combination therapy, while acral melanoma with lower BRAF mutation received anti-PD-1 inhibitors." (PMID 39123482, 2024). "However, because BRAF mutation is less common in acral melanoma, BRAF inhibitors are not generally useful for their treatment." (PMID 35997352, 2022). "Interestingly, the key genomic alterations of acral melanomas described in a previous study (such as the highest proportion of triple-WT tumors, common KIT alterations, and lower frequencies of BRAF/RAS hotspot mutations) are consistent with the characteristics of the UV-low cluster in this study." (PMID 36246650, 2022). "However, the prognostic role of BRAF mutation in acral melanoma has not been fully elucidated." (PMID 32143442, 2020).
acral melanoma (continued). "When it comes to acral melanoma, cyclin D1 has been reported to be overexpressed, resulting in constitutively activated MAPK signaling pathway without NRAS or BRAF mutations." (PMID 35484605, 2022). "Recurrent non-V600E BRAF, KIT, NF1, and TERT promoter mutations, present in acral melanoma, were not identified." (PMID 30995742, 2019). "Unlike BRAF, all RAS mutations have been identified in acral melanomas." (PMID 32083130, 2020). "As in cutaneous and acral melanoma, the mutational profile categorizes MM into different molecular groups: BRAF-mutated; RAS-mutated; NF1-loss; and triple wild-type (absence of mutations in BRAF, RAS and NF1; but the presence of KIT mutations and/or amplifications)." (PMID 37773078, 2023). "The situation of mucosal and acral melanoma patients is further complicated by the fact that these tumors are often triple wild-type tumors, i.e., without a BRAFV600E/K, NRAS or NF1 mutation, and therefore not qualified for targeted therapy with BRAF and MEK inhibitors." (PMID 32110946, 2020).
gastric cancer (62 papers, 2005 to 2026). A primary or metastatic malignant neoplasm involving the stomach. "This pathway is frequently altered in cancers, with RTK-RAS pathway alterations occurring in approximately 37% of gastric cancers and BRAF mutations in up to 11%." (PMID 40729043, 2025). "BRAF exon 15 was sequenced in a low-grade atypia polyp and hyperplastic polyp-associated gastric cancer (cases 2 and 3)." (PMID 34884530, 2021). "The results of this study reaffirm the significance of BRAF mutations as oncogenic drivers in gastric cancer and highlight the need to investigate HPAGC in a large number of GHP cases to determine the clinical significance of our findings." (PMID 34884530, 2021). "In sporadic colon and gastric carcinoma, BRAF mutation and the epigenetic inactivation of MLH1 expression by promoter methylation result in MMR deficiency." (PMID 34692533, 2021). "This study provides more data support for clinical research on KRAS/NRAS/BRAF mutation in CRCs or gastric cancers." (PMID 30416987, 2018). "This is the first paper reporting BRAF mutation in a Korean population with colorectal- and stomach cancer." (PMID 24759670, 2013). "In the present study, we have showed that RASSF2 methylation is frequent in gastric cancer, despite the rarity of K-ras/BRAF mutations in this tumour." (PMID 16265349, 2005). "Molecular subtyping plays a critical role in guiding combination therapy, as evidenced by the use of Trastuzumab combined with chemotherapy as the standard treatment for HER2-positive gastric cancer, as well as emerging strategies targeting BRAF mutations, KRAS mutations, and MSI-H/dMMR status." (PMID 41361128, 2025). "BRAF V600E mutations occur in approximately 2%–5% of human gastric cancers and are associated with microsatellite instability and better response to immunotherapy, making this comparison between KRAS and BRAF particularly relevant for understanding pathway-specific effects." (PMID 40673273, 2025). "However, BRAF mutations occur at a very low frequency in gastric cancer, with only 2.9% of screened cases exhibiting a BRAF mutation." (PMID 34884530, 2021). "The main purpose of this study is to investigate the mutation status and distribution of KRAS/NRAS/BRAF in Chinese colorectal and gastric cancers, and to explore the histopathological changes and related immunohistochemical marker changes caused by these mutations." (PMID 30416987, 2018). "There are few studies on the mutations rate of KRAS/NRAS/BRAF in gastric cancer." (PMID 30416987, 2018). "In this study we found 1 out of 34 gastric cancer cases with BRAF mutation." (PMID 30416987, 2018). "KRAS is mutated in a significant proportion but BRAF is mutated less frequently in gastric cancers." (PMID 27437872, 2016). "KRAS-addicted and BRAF-impaired gastric cancer cells were particularly susceptible." (PMID 27437872, 2016). "Finally, highly recurrent mutations in MSI tumors, such as those affecting RNF43 and BRAF in gastric cancers were associated with high number of clonal and subclonal mutations, consistent with MSI tumors having a higher mutational load than micro-satellite stable tumors." (PMID 30212491, 2018). "While inhibitors targeting components of the MAPK pathway (e.g., MEK and BRAF) have shown some clinical benefit in colorectal cancers, their efficacy as single agents in gastric cancer is limited." (PMID 40729043, 2025). "We found that PDLIM3 expression was positively correlated with such markers including PI3K, PTEN, PKB-γ, and BRAF in gastric cancer." (PMID 35647201, 2022). "Direct sequencing of gastric cancer specimens revealed the proportion of KRAS, BRAF, and PIK3CA mutations." (PMID 26207151, 2015). "For example, BRAF, KRAS, and PIK3CA, a set of rarely identified mutations in sporadic gastric cancers, have recently been reported in the microsatellite subsets of cancer." (PMID 25025766, 2014).
gastric cancer (continued). "In the present study, multiple primary cancer patients with colorectal- and stomach cancer were selected for BRAF analysis." (PMID 24759670, 2013). "Thus, it is possible that BRAF V600E CRCs depict a WNT activation mechanism similar to that observed in gastric cancer." (PMID 40102611, 2025). "Additionally, it is worth noting that KRAS mutations have also been established in gastric cancer, and alterations in the RAS pathway, caused by both RAS and BRAF mutations, play a role in the pathogenesis of gastric cancer." (PMID 39673361, 2024). "KRAS/NRAS/BRAF mutations were not significantly related to patients' age analyzed by Student's t-test or gender analyzed by Chi-square test in gastric cancer." (PMID 30416987, 2018). "Gastric cancers could harbor RAS mutation in 8–25% of cases and its presence could induce a paradoxical MAPK pathway activation during BRAF inhibitors therapy." (PMID 26981153, 2016). "Examples include clinical trials in HER2 positive gastric cancer, the Viktory umbrella trial in gastric cancer, the approval of targeted therapies for cholangiocarcinomas with FGFR2 fusions or rearrangements, or the use of a triple targeted therapy in BRAF mutated colon cancer." (PMID 34637026, 2021). "Our demonstration that type I IGF receptor knockdown prevents proliferation of BRAF-impaired MKN74 gastric cancer cells suggests that BRAF-impaired cells may have a similar dependency upon activation of IGF signal transduction to that reported for RAS-mutant cells." (PMID 27437872, 2016). "In the Venn diagram intersection of recognized targets about identified chemical compounds and gastric cancer, a total of 23 gastric cancer genes are acquired among which the top six genes ABCG2, MUTHY, TRET, POLE, BRAF and G, and FGFR2 were used to produce Venn diagram." (PMID 36500601, 2022). "Albeit rare in gastric cancers, BRAF mutations were seen at similar rates between SBA and CRC; however, unlike CRC where the majority of BRAF alterations were V600E mutations, most BRAF-altered SBAs harbored inactivating non-V600E mutations." (PMID 35267592, 2022). "In all 34 gastric cancer samples, neither KRAS nor NRAS mutation was detected, and only 1 sample (2.9%) was detected to have a mutation in BRAF exon 15 codon 600 600Glu." (PMID 30416987, 2018). "For absence of NRAS, KRAS and BRAF mutation, SGC7901 and BGC823 gastric cancer cells were relative resistance to AZD6244 in vitro." (PMID 26567773, 2015).